IL6 (interleukin 6)
Diseases named in the same sentence as IL6 in open-access papers (continued):
Sharing a sentence is not in itself a finding about the gene and the disease.
tumor (continued). "In 13 patients we could observe a parallel increase of tumor marker S100B and of the immune activation marker IL-6 in the serum." (PMID 32188047, 2020). "Furthermore, MDSC and tumor cell cross-talk enhances IL-6 production within tumor microenvironment, while IL-10, produced by MDSCs, increases M2-like TAMs." (PMID 32824865, 2020). "This increment of systemic IL-6 in EAC patients has been reported to be caused by the infiltration of monocytes and macrophages within in the tumor microenvironment as well as by the tumor cells themselves." (PMID 32298379, 2020). "Interleukin-6 (IL-6) affects the key parameters of oncogenesis, which increases the cell resistance to apoptosis, the proliferation of cancer cells, angiogenesis, invasion, malignancy, and the ability of tumor cells to respond to anticancer therapy." (PMID 32138303, 2020). "In similarity, Notch activation could stimulate IL-6-induced pathways, and in parallel the reciprocal direction was active, both leading to pro-tumor activities in BC." (PMID 32605277, 2020). "IL-6 affects the key parameters of oncogenesis, which increases cell resistance to apoptosis, the proliferation of cancer cells, angiogenesis, invasion, malignancy, and the ability of tumor cells to respond to anticancer therapies." (PMID 32138303, 2020). "Pro-inflammatory molecules, such as interleukin-6 (IL-6), tumor necrosis factor alpha (TNFα), IL-1, and interferon-γ, derived from the immune system or from the tumor itself and glucocorticoids, are increased in plasma of rodents and patients with different cancers." (PMID 33255345, 2020). "IL6 is a prominent immunosuppressor expressed in DCs, which may support the escape of tumor cells from the immunosurveillance in the TME of CRC." (PMID 33419310, 2020). "IL-6 is an important inflammatory cytokine secreted by tumor cells or stromal cells, which is highly expressed in some tumors, and participate in a variety of malignant biological processes by activating a variety of signal pathways, such as STAT3, ERK and MAPK." (PMID 33153467, 2020). "Interestingly, an anti-IL-6 and anti-PD-L1 combination treatment prolonged tumor-bearing mouse survival, providing a novel strategy to overcome anti-PD-L1 resistance in CRC." (PMID 33384962, 2020). "The expression of IDO is sustained by an autocrine loop in the presence of AhR and KYNA in tumor infiltrating tolerogenic DCs and a positive feedback loop controlled by AhR drives IL-6 expression, and it sustains IDO expression and KYN production in tumor cells." (PMID 32012948, 2020). "Finally, IL-6 is recognized as one of the main drivers of cachexia and muscle atrophy during cancer, as administration of neutralizing IL-6 antibodies in C26 mice prevents the muscular atrophy despite a slight increase in tumor mass." (PMID 33142864, 2020). "IL-6 level has been supposed to be a measure of tumor invasiveness and immune-suppression." (PMID 32468851, 2020). "Furthermore, they observed the overexpression of IL-6 in HPV-positive tumours compared to HPV-negative tumours." (PMID 32322596, 2020). "Dynamic changes in the values of tumor necrosis factor-alpha and IL-6 could reflect the cancer prognosis, depending on the tumor type, clinical progression, and cancer therapy." (PMID 32637353, 2020). "In addition, one of the main functions of the activation of the S1PR1 signaling pathway is the continuous activation of STAT3 in the form of phosphorylation, leading to overexpression of NF-κB and IL-6, which promotes tumor development." (PMID 33101013, 2020). "Functions of IL-17 relevant to tumor involve the induction of cytokines such as IL-6 and TGF-β1." (PMID 32554855, 2020). "Additionally, miR‐328‐3p neutralized the elevated levels of TNF‐α and IL‐6 induced by hsa_circRNA_002178 in tumour tissues and serum." (PMID 31957232, 2020).
tumor (continued). "Also, stroma-derived CCL2/CCL5 induces IL-6 release from the tumor cell generating carboplatin resistance through PYK2 pathway activation (positioned upstream of the JAK1/STAT3 pathway), a critical mediator of survival pathway activation." (PMID 32499779, 2020). "IL-6 is one of the cytokines in the tumour microenvironment." (PMID 32922544, 2020). "In addition, IL-6 promotes tumor development by enhancing the T cell-mediated immune-inflammatory response, regulating gene expression, and inhibiting apoptosis in the cell through the JAK-STAT signaling pathway." (PMID 32149121, 2020). "IL-6 signaling been shown to inhibit tumor growth by mobilizing antitumor T cell immune responses." (PMID 32636744, 2020). "Moreover, various monoclonal antibodies targeting IL-6 signalling, such as Situximab and Tocilizumab, have demonstrated antitumour efficacy against cancer, further solidifying the importance of IL-6 in tumour growth." (PMID 32731620, 2020). "Indeed, secreting proinflammatory cytokines, such as IL6 and TNFα, TAMs, contribute to the “dormant inflammation” determining immunosuppression in the tumor microenvironment." (PMID 32708142, 2020). "In the context of cancer, CXCL-1, IL-8 and IL-6 were known to tune the tumour microenvironment." (PMID 33267794, 2020). "Therefore, anti-IL-6 therapy would be an interesting option to target and see if it can attenuate tumor mass, thereby reducing muscle and fat wasting." (PMID 33334063, 2020). "The induction of PD-L1 expression on tumor cells, and possibly on other cell types, by IL-6 might represent an important immunosuppressive mechanism facilitating the escape of MM cells from immune surveillance." (PMID 32922390, 2020). "Anticancer effects of these compounds and their combination with cisplatin were assessed in this tumor mouse model with bioluminescent signaling and histopathology, and a cytokine assay was used to examine expression of inflammatory cytokines IL-1β, IL-6, IL-10, and TNF-α from plasma samples." (PMID 32174830, 2020). "This key difference may reveal important differences in the effect of IL-6 on tumor cell proliferation in vitro and suggests that the ability of IL-6 to promote proliferation is dependent upon the environment of the tumor cell." (PMID 32023849, 2020). "However, AAT induced TLR4 levels and enhanced LPS effects on the production of IL-6, a tumor-promoting cytokine." (PMID 32533048, 2020). "Here, miR‐3473b inhibitor significantly reduced the exosome‐mediated inflammatory genes including Il6, Ccl1, Ccl2, Ccl5 and Cxcl2 expression in fibroblasts, which suggest the potential role of exosomal miR‐3473b in establishing tumour‐promoting inflammation environment." (PMID 32449597, 2020). "IL-6 has been recognized as a pleiotropic cytokine with an obvious tumor-promoting effect." (PMID 31942188, 2020). "Activated NFkB plays a key role in various cancer progression and could enhance IL6 secretion in tumor microenvironment." (PMID 32963220, 2020). "FABP4 is secreted from both PCa cells and adipocytes surrounding PCa tumors, and is believed to either shuttle fatty acids between adipocytes and tumor cells or act as an inducer of MMPs from cancer cells and cytokines (e.g., IL‐6, IL‐8) from stroma cells to promote invasion and metastasis." (PMID 33031638, 2020). "Finally, our study shows that we can target the IL6-induced lactate efflux from tumor to revert the immune-evasive microenvironment to an immune-supportive one and thus augment outcomes of checkpoint inhibitor therapy." (PMID 33177492, 2020). "For this reason, we investigated whether miR-216a is involved in the crosstalk between cancer cells and the tumor microenvironment through the regulation of inflammatory cytokines IL-6." (PMID 32230799, 2020). "IL-6 alone or together with HGF significantly enhanced tumor invasiveness." (PMID 32792856, 2020).
tumor (continued). "In the tumor microenvironment, the IL-6 signaling pathway affects a variety of stromal cells, including endothelial cells, fibroblasts, and cells of the immune system, which are active participants in angiogenesis and inflammatory and immune-suppressive responses." (PMID 33322216, 2020). "Recent evidence indicates that IL-6 plays an indispensable role in T cell infiltration to the tumor site, which could benefit immunomodulatory therapy." (PMID 32847533, 2020). "Interestingly, tumor marker release in this patient continued despite suppression of IL-6 by prolonged corticosteroid treatment." (PMID 32188047, 2020). "Both tumor cells themselves and immune cells infiltrating tumor tissue produce IL-6." (PMID 32867390, 2020). "Furthermore, TLR2 activation stimulates MDSCs to produce IL-10, which induces macrophage polarization toward the M2 tumor-promoting phenotype, while MDSC-produced IL-6 promotes tumor metastatic growth." (PMID 33321934, 2020). "Furthermore, IL-6 has been shown to play an important role in promoting T cell trafficking to lymph nodes and to tumor sites, where they become activated and exert cytotoxic effector activity." (PMID 32636744, 2020). "Indeed, in our experimental system, chemotherapy promoted an increase in tumor IL-6 expression, which was mitigated by the incorporation of EXER." (PMID 33233839, 2020). "IL‐6 is a pleiotropic cytokine, highly secreted by tumor stromal cells, including MSCs." (PMID 31608444, 2020). "IL6 also influences the proliferation of normal and tumor-derived cells." (PMID 33374146, 2020). "Increased IL-6 production in tumor growth and development has been demonstrated in many tumors." (PMID 33536913, 2020). "Furthermore, the IL-6 secreted by tumor cells and stromal cells contributes to tumor progression and angiogenesis, but the expression of cPLA2 in macrophages is critical to the release of IL-6 from tumor cells." (PMID 33224886, 2020). "Furthermore, we find that interference with activin A signalling in cachectic tumour‐bearing mice reduces serum levels of cancer cell‐derived IL‐6 and reverses cachexia." (PMID 31436048, 2020). "Besides the pro-proliferative and pro-survival effects of interleukin-6 (IL-6) on tumor cells, this inflammatory mediator is well known for its involvement in regulating a vast array of immune cells." (PMID 33022971, 2020). "Furthermore, TAMs are a source of cytokines such as TGF-β1, STI1 (stress inducible protein 1), EGF (epidermal growth factor), IL-6 (Interleukin 6) and IL-1β (Interleukin 1 Beta) that promote growth, migration and mesenchymal transformation of the tumor cells." (PMID 32570988, 2020). "Our findings show that targeting MDM2 attenuates IL-6 expression in tumor cells which may play a crucial role in sensitizing tumor cells to T-cell-mediated killing." (PMID 32655895, 2020). "Furthermore, CD10+GPR77+ CAFs promote successful engraftment of PDXs, and targeting these CAFs with a neutralizing anti-GPR77 antibody abolishes tumor formation and restores tumor chemosensitivity via the production of IL-6 and IL-8." (PMID 33114328, 2020). "It has been suggested that tumor size (T-stage) is an independent predictor of survival and that large tumors may secrete higher amounts of IL-6." (PMID 32899735, 2020). "The levels of IL-6 and TNFα in tumor tissues were quantitated using ELISA." (PMID 32317968, 2020). "M2-polarized tumor-associated macrophages (TAMs), myeloid derived suppressor (MDSC), regulatory T (Treg), type 17 CD4+ (Th17), type 2 CD4+ (Th2), B cells or cytokines such as IL-6, IL-10, IL-17, IL-23, are generally reported to be pro-tumorigenic." (PMID 32365499, 2020). "In addition to the IL-6-Notch interactions that promoted stemness, this axis was also found to up-regulate tumor cell motility in BC." (PMID 32605277, 2020). "Serum levels of IL-6 correlate with tumor size, staging, and metastasis in human CRC." (PMID 32357539, 2020).
tumor (continued). "Inflammatory cytokines such as tumor necrosis factor-alpha (TNF-α), transforming growth factor-beta (TGF-β), interleukin-6 (IL-6) and other cytokines/chemokines have been known to enhance tumor proliferation, activate epithelial-to-mesenchymal transition (EMT) and promote metastatic potential." (PMID 33212880, 2020). "Since IL-6 signaling in bone-disseminated tumor cells might be driven by cis- or trans-IL-6 signaling, future studies investigating the efficacy of these neutralizing antibodies on both types of signaling are of interest." (PMID 32023849, 2020). "Tumor-associated macrophage (TAM) phenotype analysis showed that microbial ablation resulted in a decrease in immune-suppressive CD206+ M2-like TAMs and an increase in M1-like TAMs, which expressed higher MHC II, CD86, TNF-α, IL-12, and IL-6." (PMID 33520714, 2020). "Moreover, chronic levels of TNF-α and IL-6 in the TME have been linked to such phenomena as T cell exhaustion and facilitated tumor growth, respectively." (PMID 33154744, 2020). "Our data revealed that TIM‐4 may be an indispensable molecule involved in the progression of IL‐6‐overexpression tumours." (PMID 32020709, 2020). "On the other hand, it was shown in an orthotopic B16.F10 melanoma model that TLR2-activated MC could also inhibit tumor growth by an IL-6-dependent mechanism." (PMID 31256327, 2020). "The presence of cancer-promoting cytokines and chemokines, such as IL-6, IL-8, GRO-alpha, MIP-1α, MIP-1β, angiopoetin-2, and VEGF, which are associated with tumor growth, metastatic properties, and a poor prognosis, was detected in the supernatants collected from both ES-2 cells and OAW-42 cells." (PMID 33266317, 2020). "While IL-1β and IL-6 have been linked to the generation of MDSC inside tumor tissues, CX3CL1 and CCL22 have been found to induce the recruitment of MDSCs into the tumor microenvironment in tumor-bearing hosts." (PMID 32632113, 2020). "The results showed that several cytokines reported to play important roles in tumor promotion, such as IL6, IL8, MCP1, and GRO (CXCL1, 2, 3), exhibited upregulated expression in the LY2835219 monotherapy group and downregulated expression in the combination therapy group." (PMID 33116117, 2020). "While normal NKTs have anti-tumor effects, IL-6+ IL-10+ NKT cells lose these functions." (PMID 32178454, 2020). "Moreover, the secretion of IL-6 into the tumor mass contributes to a positive feedback loop of growth and invasion between CAFs and breast epithelial cells." (PMID 32604738, 2020). "It is known that tumor cells secrete a widely spectrum of substance, including interleukin-1 (IL-1), interleukin-6 (IL-6), granulocyte-macrophage colony-stimulating factor (GM-CSF), granulocyte colony-stimulating factor (G-CSF), able to mediate the interaction with platelet activation." (PMID 33346231, 2020). "Moreover, atorvastatin treatment decreased tumor growth and weight in an HCC xenograft animal model, which were associated with decreased IL-6 and TERT expression and STAT3 phosphorylation and increased β-gal expression and SA-β-gal activity in tumors." (PMID 32257389, 2020). "SAA may also favor tumor development by limiting immune anti-tumor by stimulating the growth of regulatory T cells in a process involving IL-1β and IL-6 induction in monocyte." (PMID 32517794, 2020). "Increased levels of IL-6 were found responsible for impaired Th1 differentiation and responses and for causing an inadequate CD4+ helper T-cell activity for CD8+ T-cells, resulting in limited tumor elimination." (PMID 32604862, 2020). "However, it has been seen that blocking single cytokines induces limited effects as both IL-6 and IL-8 are crucial for tumor growth and the expression of these genes combined with dismal prognosis in breast cancer patients." (PMID 32211043, 2020).
tumor (continued). "However, a number of key proinflammatory cytokines, such as IL-1β and IL-6, have been reported to promote tumor progression through the mobilization of MDSCs, the contribution to chronic inflammation and the stimulation of angiogenesis." (PMID 32733461, 2020). "ETO treatment of cancer cells activates the IL-6/JAK1/STAT3 pathway that may mediates communication between tumor cells and the microenvironment." (PMID 32059469, 2020). "Various studies have shown Bazedoxifene could inhibit tumor growth by targeting the IL-6/GP130/STAT3 signaling pathway." (PMID 32362823, 2020). "By the use of species‐specific ELISAs, we also found that tumour‐bearing mice were subjected to a massive rise in the level of serum IL‐6 derived from the cancer cells (human IL‐6) and a significant, but clearly less substantial, increase in host‐derived murine IL‐6." (PMID 31436048, 2020). "Interestingly, a single intratumoral injection of a ZFP36L1 fusion protein was shown to be effective at decreasing VEGF, acidic FGF, TNFα, IL-1α, and IL-6, as well as at reducing tumor growth." (PMID 32545247, 2020). "IL-6 is produced by various types of cell such as T-cells, B-cells, monocytes, fibroblasts, keratinocytes, endothelial cells, mesangial cells, adipocytes and some tumor cells." (PMID 32209102, 2020). "In addition, various tumor-related humoral factors and pro-inflammatory cytokines such as interleukin (IL)-1, IL-3 and IL-6 have been shown to stimulate thrombopoiesis in cancer patients." (PMID 33160368, 2020). "PCa tumours which have metastasized to the bone have been reported to be infiltrated by immune cells which may be the source of IL6 and/or IL10." (PMID 32802517, 2020). "In addition, pro-inflammatory cytokines, including TNF-α, IL-6, and IL-1β, play key roles in regulating inflammation and tumor progression." (PMID 32679895, 2020). "Moreover, Hyp-PDT can reduce the cancer cell-secreted tumor-promoting cytokines, such as GM-CSF, IL-6, and TNF." (PMID 32340275, 2020). "This is consistent with the ability of IL-6 to stimulate tumor cell proliferation." (PMID 32528731, 2020). "However, tumor cells can domesticate these cells, and alter their maturation and activation through galectin-1 and IL-6 to confer a pro-tumorigenic phenotype that promotes tumor growth, metastasis, and immune escape." (PMID 32150875, 2020). "As a widely studied cytokine, IL-6 has pleiotropic and complex functions in tumor development." (PMID 32134471, 2020). "However, in cancer, VEGF, M-CSF, IL-6, adenosine and hypoxia accumulated in the tumor microenvironment affect DC functions, leading to the enrichment of immature, functionally incompetent DC." (PMID 32878277, 2020). "In addition to its pro-tumorigenic effects, IL-6 has also been shown to exert anti-tumor effects by increasing T cell trafficking and adhesiveness to the tumor endothelium." (PMID 33194755, 2020). "Our results showed that increased lactate was produced by tumor cells in the presence of IL6." (PMID 33177492, 2020). "NPY increases MDSCs in the tumor site, and, induces IL6 release by tumor cells and MDSCs." (PMID 32516941, 2020). "Notably, tumor burden was significantly reduced by the administration of IL-6 neutralising antibodies." (PMID 32528288, 2020). "IL-6 is reported to be the most important tumor-promoting cytokine." (PMID 33167343, 2020). "TTP mainly functions as a tumor suppressor by targeting mRNAs encoding proteins related to the cell cycle (Cyclin B1 and D1), cell death and proliferation (Bcl-2 and cIAP), angiogenesis (VEGF), and EMT (Snail, Twist1, ZEB1, SOX9, MACC1, MMP2, MMP9, and IL-6)." (PMID 32967226, 2020). "LncRNA CamK-A can facilitate the secretion of growth factors and cytokines derived from tumor cells to accelerate the transcription of multiple NF-κB downstream genes such as IL-6, VEGF etc., which result in angiogenesis, infiltrated macrophage recruitment and tumor microenvironment remodeling." (PMID 33148302, 2020).